INS (insulin)
Diseases named in the same sentence as INS in open-access papers (continued):
Sharing a sentence is not in itself a finding about the gene and the disease.
Obesity (continued). "Therefore, consumption of the novel polyherbal formulation, 18KHT01, may be effective for the management of human obesity and its comorbidities such as insulin resistance and oxidative stress." (PMID 34975503, 2021). "Additionally, obesity-related inflammation may have potential implications for ovarian physiology due to the dysregulated adipokine secretion, affecting insulin sensitivity." (PMID 34071499, 2021). "Furthermore, supplementing methyl donor to lactating rats was shown to decrease maternal obesity induced hepatic adipose deposition in offspring, and significantly decrease blood glucose level in the next generation by downregulating the insulin resistance pathway." (PMID 34828259, 2021). "Moreover, disulfiram, which is used for the treatment of alcoholism, has been shown to normalize fat mass and insulin sensitivity in diet-induced obese mice and repurposing of this drug in the clinic has been suggested as a strategy to treat obesity and related metabolic complications." (PMID 34230558, 2021). "Significant differences were found between HF and HF + LGB groups in pathways involved in lipid and carbohydrate metabolism, insulin resistance, oxidation-reduction process and inflammation suggesting that lingonberry has potential to prevent metabolic adverse effects induced by developing obesity." (PMID 34835949, 2021). "Obesity induces a state of chronic, low-grade inflammation in the adipose tissue that is accompanied by the local secretion of several pro-inflammatory cytokines and chemokines, especially TNFα, attenuating insulin action and resulting in insulin resistance through activation of the JNK pathway." (PMID 34685582, 2021). "Interestingly, the decrease in elevated insulin levels and reduction in fat percentage could reverse obesity in older people." (PMID 34676021, 2021). "Along these lines, vaspin-derived N-terminal peptides may contribute to increase local proliferation of preadipocytes during adipose tissue expansion, thereby counteracting adipocyte hypertrophy, inflammation and dysfunction and preserving insulin sensitivity in obesity." (PMID 33866927, 2021). "Additionally, depletion of the homeostatic commensal microbiome can impair thermogenesis, and amelioration of an obesity-associated microbiome or supplementation with SCFA butyrate can restore thermogenic processes and improve obesity-associated glucose tolerance and insulin sensitivity." (PMID 33972511, 2021). "In the same study, obese children had significantly higher insulin concentrations, which raises the question of whether the observed changes in n-3 PUFA metabolism may be attributed to the hyperinsulinemia associated with obesity." (PMID 34638763, 2021). "Ay mice develop obesity-associated hyperleptinemia and leptin resistance; partial restoration of leptin sensitivity in FGF21-treated male mice may contribute to lowering blood insulin levels in males." (PMID 34943946, 2021). "In addition, if fat cells were already resistant to insulin in the early phase, it is difficult to understand how hyperinsulinemia could stimulate lipogenesis and induce obesity by driving calories into fat cells." (PMID 34360563, 2021). "Therefore, this therapeutic strategy could improve the management of patients with T2DM and DKD with obesity or preserved insulin reserve, as it can be safely administered in those patients with impaired kidney function (eGFR > 15 mL/min/1.73 m2)." (PMID 34070103, 2021). "A better understanding of alterations in brain glucose metabolism in health, obesity, and neurodegeneration, and the relationships between insulin resistance and central nervous system glucose metabolism may be an important step for the battle against metabolic and cognitive disorders." (PMID 33917464, 2021).
Obesity (continued). "However, as internationally agreed reference measures for (ab)normal insulin sensitivity during childhood are still lacking, this systematic review assembled metabolite patterns of obesity and -related IR towards prompt signalisation of high-risk phenotypes." (PMID 34742239, 2021). "Growing evidence suggests that insulin and leptin play significant physiological roles in cognition, and these signaling pathways may be promising therapeutic targets to alleviate cognitive impairment accompanied by obesity and MetS." (PMID 34795562, 2021). "Therefore, while data on adiposity appear to be incongruous between mouse models with ATX, LPP3, and LPA receptor modulation, glucose homeostasis and insulin function appear to be generally improved with ATX/LPA receptor inactivation during diet-induced obesity." (PMID 34502491, 2021). "Additionally, a positive association of plasma insulin and C-peptide with postmenopausal breast cancer risk has been reported, and this was independent of obesity status (at least in some studies)." (PMID 34485137, 2021). "Therefore, according to our study, improvements in obesity status through exercise during puberty may be able to restore insulin resistance." (PMID 33507953, 2021). "However, CB2 receptor deficiency in aged mice induced hyperphagia associated with age-dependent obesity, and fat and liver inflammation, with no changes in insulin sensitivity." (PMID 34718828, 2021). "However, the effects of leucine supplementation and exercise on insulin resistance and inflammation in early obesity are unknown." (PMID 34054726, 2021). "Therefore, the purpose of this study was to examine the efficacy of pharmacological inhibition of Drp1 in improving skeletal muscle mitochondrial dynamics and function, insulin sensitivity, and whole‐body glucose metabolism in an obesity‐induced insulin‐resistant condition." (PMID 33904649, 2021). "Cluster 4 (denoted as hypometabolic obesity [LMO]): 134 (15%) patients characterized by high glucose (median glucose AUC: 1748 vs. 928-1030 mmol/l·min in other three subgroups) with decompensated insulin secretion (median insulin AUC: 8244 vs. 13775-47061 mU/l·min in the other three subgroups)." (PMID 34335479, 2021). "In addition, artificial sweetener may contribute to obesity by modulating the gut microbiota and stimulating basal insulin secretion." (PMID 33070213, 2021). "This occlusion of insulin-induced increases in the high-fat group suggest physiological roles for insulin in the NAc, and are consistent with the idea that physiological shifts in circulating insulin secondary to diet-induced obesity impact neural insulin sensitivity." (PMID 33514676, 2021). "Although the role of miR-124a in the development of human obesity has not been confirmed, it plays a significant role in pancreatic beta cell development and regulation of insulin secretion, and thus its aberrant expression is implicated in the pathogenesis of T2DM." (PMID 34943849, 2021). "This suggests that butyrate-producing L. salivarius may be considered as a potential treatment for obesity in infants by reducing inflammatory cytokines and regulating leptin/insulin levels, but this requires further investigations and elucidation through future RCTs." (PMID 34835958, 2021). "The decrease of Fetuin-B correlates with improvement of estimates of obesity (BMI (r = 0.337; p = 4.2 × 10−5), fat mass (r = 0.281; p = 0.002), waist circumference (r = 0.262; p = 0.002)), ΔHSI (r = 0.179; p = 0.034), whole body (ΔHOMA-IR) as well as adipose insulin sensitivity (ΔFFASupp)." (PMID 34611132, 2021). "We conclude that impaired lipid storage observed in WAT of HFD-induced obesity-resistant Mof+/− animals is neither caused by a defect in lipogenesis arising from impaired insulin signaling nor as a result of increased lipid breakdown or impaired lipid transport." (PMID 34707105, 2021).
Obesity (continued). "We have previously studied a mathematical model of glucose-insulin homeostasis to estimate insulin secretion, glucose uptake by tissues, and hepatic handling of glucose and tracked changes of the parameters of glucose-insulin homeostasis during the course of obesity in mice." (PMID 34270619, 2021). "In conclusion, obesity-associated immunometabolic factors including LDL-cholesterol, FABP4, and leptin were associated with a higher iNKT cell IFN-γ response across all disease groups, while HDL-cholesterol and insulin sensitivity (QUICKI) were associated with a higher IL-4 response." (PMID 34635725, 2021). "In the context of obesity and its related metabolic disturbances, elevated insulin levels, as observed in patient with insulin resistance and MetS, have been speculated to upregulate TMPRSS2 expression via phosphoinositide 3‐kinase/protein kinase B/androgen receptor signaling." (PMID 34269511, 2021). "It has been shown that mothers with overweight status and obesity have a higher concentration of HM insulin compared to mothers of normal weight, suggesting maternal adiposity may play a role in regulation of HM insulin concentration." (PMID 34835980, 2021). "In a freshly released study of testing NMN in human, Samuel Klein’s team conducted double-blind clinical trial and found that NMN could improve insulin sensitivity, insulin signaling and muscle tissue remodeling in the prediabetic women with overweight or obesity." (PMID 34366891, 2021). "Also, obesity impaired insulin signaling in the liver of mice; however, exercised mice restored Akt phosphorylation, demonstrating an improvement in hepatic insulin signaling." (PMID 34203825, 2021). "Therefore, we performed a secondary exploratory analysis to investigate how insulin treatment in pregnancy affects the risk of PPD in women with obesity relative to women without obesity." (PMID 33743677, 2021). "Additionally, ANGPTL3 is typically downregulated by leptin and insulin, and, therefore, resistance to leptin and insulin that generally happens in obesity may be responsible for its elevated levels." (PMID 34422408, 2021). "Altered processing of lipid species within skeletal muscle is often observed during obesity, T2DM, and other metabolic diseases with disrupted processing of species including diacylglycerols (DAGs) and ceramides associated with defects in the insulin signaling pathway." (PMID 33433056, 2021). "This could be attributed to a number of factors as obesity stimulates the activation of the renin-angiotensin-aldosterone system, an increase in sympathetic activity, which further promotes insulin and leptin resistance, and an increase in procoagulatory activity and endothelial dysfunction." (PMID 33898368, 2021). "In obesity, B2 cells and Th1-polarized T cells accumulate in visceral adipose tissue and contribute to insulin resistance, whereas B1, B-regulatory cells, Th2 and T-regulatory cells promote insulin sensitivity, and are reduced in number and/or function in obese visceral adipose tissue." (PMID 33622333, 2021). "Therefore, our results support a relationship between obesity and peripartum depression, where the potential benefit of insulin treatment may reflect positive effects on both glycemic control and on lactogenic hormone levels." (PMID 33743677, 2021). "Other animal studies which explored the relationship between gut microbiota and obesity through tryptophan-derived metabolites showed that the dysregulation of tryptophan-derived metabolites results in the development of white adipose tissue and insulin sensitivity, ultimately resulting in obesity." (PMID 34502562, 2021). "Thus, C-peptide, insulin, leptin, PAI, GIP, GLP-1, ghrelin, resistin, and visfatin are closely associated with carbohydrate and lipid metabolism and BMI in obese patients, which contributes to the formation of IR in obesity." (PMID 33959145, 2021).
Obesity (continued). "Moreover, we were not able to disclose whether the observed changes in Ig-positive cells were due to the high-fat diet originated from hyperglycemia and insulin excess (T2DM) or from excessive lipid intake (obesity)." (PMID 33503874, 2021). "Consequently, high insulin levels observed in obesity may contribute to lysosomal dysfunction by generating an increase in the expression CD36, which together contribute to obesity-associated dyslipidemia." (PMID 34957117, 2021). "In addition, as obesity could impair glucose tolerance and insulin function, an oral glucose tolerance test (OGTT) was performed to determine whether the materials would block glucose absorption in the intestine after forming a physical barrier." (PMID 34959957, 2021). "Therefore, we predicted that high-fat diet-induced obesity may blunt insulin's ability to enhance NAc excitatory transmission." (PMID 33514676, 2021). "Although it is known that abnormal lipid metabolism and adipose tissue accumulation possibly play important roles in linking obesity and T2D, the actual mechanisms are still unclear because not all obese people are insulin resistant or at high risk of diabetes." (PMID 34368359, 2021). "Therefore, our objectives are to first, identify the risk of PPD among women with and without obesity, and second, observe the effect of insulin treatment during pregnancy on the risk of PPD." (PMID 33743677, 2021). "Finally, administration of recombinant FGF-21 in rodents and humans improves the lipid profile and insulin sensitivity, indicating that this analogue may be useful in the pharmaceutical management of the complications of obesity and insulin resistance." (PMID 33924457, 2021). "Additionally, butyric acid may have beneficial impact on human health, improving insulin sensitivity, protecting against diet-induced obesity and colon cancer." (PMID 34574197, 2021). "However, the role of resistin in obesity and insulin dysregulation is highly controversial." (PMID 35011183, 2021). "In fact, their agonists may interact with components of multiple pathways in macrophages to modulate signaling crosstalk with metabolic tissues, coordinating a precise and appropriate cellular response in order to improve the insulin signaling and other obesity-related metabolic disorders." (PMID 34497585, 2021). "Furthermore, cholinergic blockade decreases basal serum insulin concentrations in obese, but not lean, mice, suggesting that elevated basal pancreatic parasympathetic efferent tone underlies obesity-induced hyperinsulinemia (Ahrén and Lundquist, 1982)." (PMID 34192533, 2021). "In those women, the indicative of obesity was BMI and waist circumference (WC) characteristics of visceral obesity, in addition to positive correlation between the concentration of leptin and WC, between the levels of resistin and insulin and the levels of resistin and HOMA." (PMID 33520042, 2021). "In subjects with obesity, plasma insulin concentrations and the RQ did not decrease after 24, as compared with 12, hours of fasting, which is consistent with the hypothesis that obesity is associated with metabolic inflexibility." (PMID 34331964, 2021). "Therefore, profound changes in dietary lipid composition and insulin sensitivity may contribute to pathologic dysregulation of myelopoiesis and are one plausible mechanistic link between cancer and obesity." (PMID 33077904, 2021). "Thus, any diet that can reduce obesity and lower insulin levels, such as the ketogenic diet, might reduce cancer risk." (PMID 34068325, 2021). "A considerable percentage of BC in postmenopausal women is due to obesity due to subclinical chronic inflammation and alterations in hormonal systems, including sex steroid hormones as well as peptide metabolic hormones, such as insulin, bioavailable insulin growth factor (IFG)-1, and adipokines." (PMID 34827610, 2021).
Obesity (continued). "Studies found that the selective intestinal FXR agonist fexaramine could improve obesity-related metabolic dysfunctions, and activate G protein-coupled bile acid receptor 1/Glucagon-like peptide-1 signaling to improve insulin sensitivity and increase adipose tissue browning." (PMID 34603061, 2021). "This relation between ADMA, obesity, and IR is further supported by interventional studies, which have shown that weight loss was associated with a lowering of circulating ADMA levels in obese individuals, which in turn was accompanied by an increase in insulin sensitivity and NO production." (PMID 34492019, 2021). "In addition, these pathways like inflammation or insulin resistance are “typical” on obesity." (PMID 34968279, 2021). "Moreover, subjects with PWS showed lower fasting insulin levels despite severe obesity grade." (PMID 33891302, 2021). "Indeed, recent studies showed that re-sensitisation of leptin signalling mediated by neutralising antibodies restores both leptin and insulin sensitivity, promoting weight lowering and thermogenic activation and thus constituting a promising therapy against leptin resistance in obesity." (PMID 34208585, 2021). "Subjects with high rates of body size growth show high levels of exposure to CRFs (e.g., obesity; high pBP, adverse lipid profile, impaired insulin sensitivity), making it difficult to determine whether (potential) arterial variations are directly or indirectly associated with growth rates." (PMID 33671380, 2021). "Butyric acid and acetic acid can prevent diet induced obesity without loss of appetite, while propionic acid can reduce food intake, and butyric acid, propionic acid and acetic acid can prevent diet induced obesity and insulin resistance." (PMID 34835972, 2021). "This is a vicious circle since obesity drives production of inflammatory markers by white adipose tissue and contributes to low-grade inflammation and endotoxemia (leakage of endotoxin in serum due to higher intestinal permeability) which can induce obesity and insulin resistance." (PMID 34063694, 2021). "The proportion of microglia that express CCR2 also increases in obesity, which may indicate their activation, or chemoattraction toward areas with fenestrated capillaries and the gradient of increased leptin, free fatty acids, or insulin." (PMID 34154608, 2021). "Interestingly, when women with obesity and insulin treatment were compared to the lean group with no insulin treatment, significance was lost, providing support to the hypothesis that insulin changes the relationship between obesity and PPD." (PMID 33743677, 2021). "The Clostridium cochlearium and Lactobacillus acidophilus administration might restored imbalance between the anti-inflammatory and pro-inflammatory states of adipose tissue induced by obesity, leading to an improvement of the insulin sensitivity and glucose homeostasis." (PMID 34926547, 2021). "In fact, insulin-resistant endothelium and the resultant impairment in PI3K-AKT-eNOS signaling have been proposed to underlie much of the endothelial dysfunction observed in the setting of obesity and T2D, predisposing to hypertension, atherosclerosis, and vascular disease." (PMID 33629656, 2021). "Thus, leading to the hypothesis that elevated AMPK activity in GF mice may contribute to enhanced insulin sensitivity and obesity resistance." (PMID 33222397, 2021). "As macrophages accumulate in tissues (e.g., adipocytes, and islets) during obesity, they produce pro-inflammatory cytokines (e.g., TNF-α, IL-1β, and IFN-γ) that cause biochemical and physiological effects locally within the tissues and systemically, leading to insulin resistance." (PMID 34064822, 2021). "Of note, the limitations of diet-induced obesity mice are poor standardization, long duration, and overtly obese when compared with the patients, although there are several similarities between mice and patients, including the obesity characteristics and insulin resistance." (PMID 35010955, 2021).